LCN2 (lipocalin 2)
Diseases named in the same sentence as LCN2 in open-access papers (continued):
Sharing a sentence is not in itself a finding about the gene and the disease.
tumor (continued). "Recent evidence suggests that LCN2 contributes to several tumor-promoting processes such as angiogenesis, therapy resistance and modulation of the tumor microenvironment." (PMID 41303420, 2025). "LCN2 specifically binds to siderophores, altering intracellular iron levels, which plays a critical regulatory role in tumor proliferation and metastasis via altering TME-cells survival status." (PMID 40313933, 2025). "The results revealed that the expression of ACTN4 and LCN2 was positive in the cytoplasm and partly in the nucleus and that the expression level of ACTN4 was low, whereas the expression level of LCN2 was high in tumor tissue." (PMID 39931061, 2025). "With tumor progression resembling embryonic development, LCN2 serves as a key gene that regulates this process and plays different roles in different kinds of tumors and different progression stages." (PMID 40109857, 2025). "Since LCN2 is a secreted protein, the possibility exists that iron-loaded LCN2 is rapidly captured by tumor cells due to the enhanced expression of SLC22A17, the LCN2 receptor." (PMID 40109379, 2025). "Previous work from multiple laboratories has demonstrated that LCN2 promotes invasion and metastasis in multiple tumor types." (PMID 40356520, 2025). "This study revealed that serum lipocalin 2 levels decrease in breast cancer patients with increased tumor expression of the ER and PR receptors, it also indicates the collaboration and the cross-talk of iron transport proteins to deliver it to cancer cells." (PMID 40450119, 2025). "This phenotype was reversed at a later timepoint which coincided with downregulation of immunosuppressive Cd274+Lcn2+ neutrophils and upregulation of anti-tumor P2rx1+Nrf2− neutrophils." (PMID 40568084, 2025). "LCN2 triggered by bacterial infection can bind to bacterial iron‐loaded siderophores and enhance tumor cell proliferation." (PMID 39511728, 2025). "Activated neutrophils release LCN2, which further enhances tumor aggressiveness and promotes a pro-tumor inflammatory milieu." (PMID 41303420, 2025). "Neutrophils stimulated by these factors exhibited increased LCN2 secretion, which subsequently contributed to tumor stemness." (PMID 41303420, 2025). "In this regard, the pattern of temporal LCN2 expression during tumor development indicates the role of LCN2." (PMID 40109857, 2025). "scRNA-seq also revealed the downregulation of Ptgs2 in the predominant tumor cluster 0 and an overall decrease in the immunosuppressive Cd274+ Lcn2+ Ptgs2+ neutrophil cluster 0 in the CAR-T-treated group." (PMID 40568084, 2025). "During initial stages of carcinogenesis, pro‐inflammatory cytokines promote LCN2 production and iron sequestration in macrophages and facilitate accelerated production of reactive oxygen species as a first‐line anti‐tumor defense mechanism." (PMID 39511728, 2025). "Lipocalin-2 (LCN2) is a promising therapeutic target for IBC due to its role in promoting tumor invasiveness, angiogenesis, and the inflammatory tumor microenvironment characteristic of IBC." (PMID 40732340, 2025). "This formulation was effectively internalized by HER2+ IBC cells, significantly reducing LCN2 mRNA levels and destroying the tumor emboli." (PMID 40732340, 2025). "Preclinically, combining RT with LCN2-neutralizing antibodies elicited synergistic anti-tumor immunity." (PMID 41436429, 2025). "The discrepancies among these studies demonstrate that LCN2 represents an important driver of tumor malignant progression, but there are still some limitations." (PMID 40313933, 2025). "It is widely thought that LCN2 is mainly involved in regulating tumor metastasis by promoting or suppressing the progression of EMT and MET." (PMID 40313933, 2025). "The postoperative decrease in urinary LCN2 levels further indicates its tumour origin and prognostic value." (PMID 41363723, 2025). "An in vivo xenograft model was established to investigate the effects of LCN2 on tumor growth and metastasis." (PMID 40211270, 2025).
tumor (continued). "Through the induction of LCN2, EGFRvIII-expressing tumor cells actively recruit and activate fibroblasts, which subsequently enhance tumor cell aggressiveness." (PMID 40472740, 2025). "Here, we demonstrate that upregulation of lipocalin-2 (LCN2) in tumor cells promotes brain metastatic progression by orchestrating crosstalk among metastatic tumor cells, astrocytes, and macrophages." (PMID 41436606, 2025). "The results indicated that LCN2 expression was significantly lower in LN+ GC tissues than in LN–GC tissues and was strongly correlated with tumor pathological grade." (PMID 40884261, 2025). "Recruited macrophages, in turn, activate IL-1β/IL-1R signaling in tumor cells, which further enhances LCN2 expression." (PMID 41436606, 2025). "These N2 neutrophils activate STAT3-activated lipocalin 2 (LCN2), which facilitates the formation of the tumor microenvironment and supports tumor colonization during metastasis." (PMID 40977686, 2025). "The association between LCN2 and metabolic reprogramming in TNBC remains largely unexplored, with its effects appearing to be tumor- and tissue-specific." (PMID 41303420, 2025). "To determine the impact of Herceptin and LCN2 targeting on the disruption of tumor emboli, we treated IC3 tumor emboli with Herceptin-conjugated liposomes loaded with siRNA-NC or siRNA-LCN2." (PMID 40732340, 2025). "The iron scavenging effect of LCN2 is involved in increased tumor size in the distal small intestine." (PMID 40109857, 2025). "We observed that VEGF-A expression and secretion were elevated in tumor cells with high LCN2 expression, which was correlated with increased microvascular density in BM model mice." (PMID 41436606, 2025). "The authors found a correlation between unmethylated LCN2 promoters and significantly higher microvessel density, indicating increased tumor angiogenesis." (PMID 41303420, 2025). "LCN2 has emerged as a pivotal regulator in BC and its multifaceted influence on tumor progression, metastasis and cellular plasticity highlights its particular relevance for TNBC." (PMID 41303420, 2025). "Cancer cells deploy this mechanism by capturing LCN2-bound iron, leading to increased tumor proliferation." (PMID 41303420, 2025). "By promoting CAF activation, ECM remodeling, and STAT3-mediated signaling, LCN2 establishes a crucial link between EGFRvIII-expressing tumor cells and stromal reprogramming, ultimately enhancing tumor growth and invasion." (PMID 40472740, 2025). "A significant finding was that postoperative urinary LCN2 levels measured 1 month after surgery were markedly reduced compared to preoperative levels, suggesting a tumour‐derived origin." (PMID 41363723, 2025). "In summary, LCN2 is dispensable for BBB transmigration but is essential for promoting tumor growth within the brain microenvironment." (PMID 41436606, 2025). "Remarkably, the supernatant of tumor monocytes was able to induce a higher expression of CRC EGC marker genes (Lcn2, Timp1, Ccl2, and Il6) compared to control BM-derived monocytes in an IL-1R-dependent manner." (PMID 39030280, 2024). "Immunohistochemistry showed LCN2, snail, and vimentin protein expression were increased and E-cadherin protein expression was decreased in tumor tissues derived from RGS10-depleted SKBR3 cells compared to NC." (PMID 39145770, 2024). "Expression of LCN2 proteins was suppressed by blocking the Wnt and NF-κB signaling pathways, indicating that these pathways are essential in LCN2-mediated tumor cell invasion and metastasis." (PMID 39040042, 2024). "Clinically, LCN2 expression in GC negatively correlates with tumor grade, poor prognosis, SPARC expression, and c-Jun expression." (PMID 39424639, 2024). "LCN2 has been implicated in regulating TME interactions and tumor progression in well-defined preclinical models." (PMID 39188682, 2024).
tumor (continued). "Previous studies have indicated that Melittin inhibits tumor cell migration and enhances cisplatin sensitivity by suppressing IL-17 signaling pathway gene LCN2 in castration-resistant prostate cancer." (PMID 38833027, 2024). "The IroA-E. coli showed enhanced resistance to LCN2 and significantly improved the anti-tumor activity in mice." (PMID 38747577, 2024). "In the context of inflammatory breast cancer (IBC), a reduction in LCN2 expression was found to markedly suppress tumor growth, invasion, and metastatic spread to the brain in both in vitro and in vivo studies." (PMID 39188682, 2024). "An in vivo study in an orthotopic TNBC tumor model showed that CRISPR knockout of Lcn2 reached >81% by tNLGs, resulting in significant tumor growth suppression (>77%)." (PMID 38893132, 2024). "Some studies suggest that LCN2 promotes cancer growth, while others propose its role as a tumor suppressor." (PMID 39850877, 2024). "LCN2 promoted IBC tumor aggressiveness in vitro and LCN2 depletion in IBC cell lines decreased colony formation, migration, and cancer stem cell populations." (PMID 39040042, 2024). "LCN2 targeted therapy demonstrated robust anti-tumor effects in both the in vitro 3D biomimetic chip and in vivo mouse model, including inhibition of angiogenesis, promotion of sorafenib sensitivity, and enhancement of nature killer (NK)-cell cytotoxicity." (PMID 39188682, 2024). "LCN2, a member of the LCN family of proteins involved in various cellular functions, has been extensively studied due to its close association with tumor development." (PMID 39850877, 2024). "The second interaction triggers ‘nutritional immunity’ in macrophages to deploy the high-affinity iron transporter lipocalin-2 to capture and sequester iron in the tumor microenvironment." (PMID 39057460, 2024). "In brain microenvironment, LCN2 undermines the blood-brain barrier and facilitates tumor seeding in the brain by modulating the behavior of key cellular components." (PMID 39188682, 2024). "Taken together, our study suggests that LCN2 negatively regulates the JNK/c-Jun signaling pathway to exert its tumor-inhibitory functions in GC." (PMID 39424639, 2024). "Inhibition of LCN2 function using LCN2 monoclonal antibody reduces in vitro chemoresistance and transformation, and reduces tumor progression and chemoresistance in xenograft mouse models." (PMID 39359721, 2024). "Lipocalin 2 (Lcn2) overexpression in metastatic BC has a principal role in progression by inducing the epithelial-to-mesenchymal transition and enhancing tumor angiogenesis." (PMID 39795985, 2024). "LCN2, which belongs to the LCN family of proteins involved in various cellular functions, has been extensively studied and is closely linked to tumor development." (PMID 39424639, 2024). "Interventions such as targeting LCN2 with specific monoclonal antibodies or siRNA delivery systems have shown promise in curbing tumor growth and metastasis." (PMID 39188682, 2024). "We also found that the colonization of E. coli in the tumor led to an increased expression of lipocalin 2 (LCN2), a host protein that can sequester the enterobactin." (PMID 38747577, 2024). "Meanwhile, the results of WB, flow cytometry, immunohistochemistry, and Perls blue staining (DAB enhanced) analysis of tumor tissue showed that C5aRA can inhibit M2 polarization, ER stress, and LCN2 expression, thereby reducing iron deposition in the tumor." (PMID 39850877, 2024). "Among these cytokines, tumor cell-derived G-CSF stands out as the primary cytokine responsible for upregulating LCN2 expression in neutrophils and inducing their reprogramming into immunosuppressive traits." (PMID 39188682, 2024). "Studies show that iron bound to LCN2 released by macrophages increases MCF-7 tumor cell proliferation, while LCN2 knockdown reduces both iron release and cell proliferation." (PMID 39188682, 2024).
tumor (continued). "LCN2 induced T-cell apoptosis by reducing cellular iron concentration; moreover, the iron that was transported to the tumor microenvironment aided tumor cell proliferation, promoting tumor development." (PMID 38072118, 2023). "Overall, numerous studies have shown that Lcn-2 facilitates tumorigenesis by enhancing tumor cell growth and survival, and by increasing cellular resistance to chemotherapeutics and iron-induced toxicity." (PMID 37958332, 2023). "These authors also discovered that sorafenib, an antineoplastic drug, was more potent when administered in combination with anti-Lcn-2 neutralizing antibodies, which lead to an increase in lipid peroxidation and ferroptosis in tumor tissue." (PMID 37958332, 2023). "The aim of this review is to summarize the available information regarding Lipocalin-2 in tumor progression." (PMID 37958332, 2023). "Depletion of LCN2 dramatically attenuated the proliferation, colony formation and migration of tumor cells." (PMID 37684641, 2023). "This study fills in these blanks to expand our understanding of the functions of LCN2 in the tumor immune microenvironment." (PMID 38072118, 2023). "The same conclusions were drawn from human tumor samples, whereby xCT and Lcn-2 levels exhibited a positive correlation." (PMID 37958332, 2023). "Meanwhile, tumor homogenate experiments also confirmed that LCN2 was successfully inhibited by NPs in this process." (PMID 36899380, 2023). "Concordant with this observation, orthotopic transplantation of advanced PDAC cells (KPC) into lean Lcn2−/− mice delayed tumor growth and decreased inflammation and fibrosis." (PMID 37648285, 2023). "Other studies proposed that the contribution to tumor metastasis is attributed to Lcn-2′s ability to promote EMT, which is a central process in cancer cell dissemination." (PMID 37958332, 2023). "Previous studies have shown that fecal lipocalin-2 is elevated in patients with CRC and associated with tumor progression." (PMID 38090485, 2023). "In this study, LCN2 was screened for the first time as a key DEP in tumor-infiltrating T cells, particularly in CD4+ T cells." (PMID 38072118, 2023). "Our RNA-seq analysis also identified LCN2 as one of the major factors that are secreted by neutrophils upon the stimulation of the c-Met high tumor cells." (PMID 37174093, 2023). "By using a monoclonal antibody, they inhibited the function of Lcn-2, which, in turn, decreased the chemo-resistance and tumor progression of colon carcinoma in a xenograft mouse model." (PMID 37958332, 2023). "Meanwhile, LCN2 also influenced tumor progression through immune cytokines and cholesterol metabolism." (PMID 38072118, 2023). "Numerous studies have shown that LCN2, a secreted protein, is closely related to the malignant progression of tumours." (PMID 37753805, 2023). "Tumor-bearing Lcn2 knockout mice showed reduced adipose tissue inflammation, less muscle atrophy, and decreased thermogenesis in brown adipose tissue." (PMID 37222464, 2023). "The differential functions of Lcn2 as an oncogene as well as tumor-suppressor are beyond the scope of this review and have been discussed in some detail elsewhere." (PMID 37222464, 2023). "Our results demonstrated that LCN2 has immunosuppressive functions that can promote tumor development; therefore, it is a potential immunotherapy target for CRC." (PMID 38072118, 2023). "Yet, DFO treatment was shown to impair the tumor growth and shRNA of Lcn-2, and its receptor was shown to impair the iron acquisition and proliferation of tumor cells." (PMID 37958332, 2023). "Tumor cells overexpressing LCN2 have been reported to have iron-capturing functions in leptomeningeal metastasis or to develop resistance to ferroptosis inducers in CRC." (PMID 38072118, 2023). "In this study, we analysed the effect of DFOM in ESCC tumour progression by targeting LCN2, and the LCN2/LOXL2/MMP9 complex as well." (PMID 37753805, 2023).
tumor (continued). "In comparison, sEVs were superior in tumor targeting and immune evading due to the highly expressed specific proteins on the surface, such as lipocalin-2 (LCN2) and tetraspanin protein CD47." (PMID 38031152, 2023). "We translated this finding by systemic delivery of siLCN2 by NPs, which effectively downregulated LCN2 in the tumor tissues, thereby leading to a significant inhibition of the growth and metastasis of xenografts." (PMID 36899380, 2023). "Coculture systems were used to mimic the tumor immune microenvironment and to reflect LCN2 functions in tumors." (PMID 38072118, 2023). "Proteomic analysis of LCN2-overexpressed Jurkat cells revealed that LCN2 reduced T-cell iron by regulating iron efflux, which induced T-cell apoptosis and promoted tumor cell proliferation via tumor microenvironment." (PMID 38072118, 2023). "This opposing role of Lcn-2 appears to be regulated in an iron-dependent manner, whereby holo-Lcn-2 (i.e., iron–siderophore-loaded Lcn-2), can fuel tumor growth, while apo-Lcn-2 (i.e., iron–siderophore-complex-free Lcn-2), promotes apoptosis." (PMID 37958332, 2023). "Upregulated LCN2 in tumor cells within cerebrospinal fluid allowed these cells to collect limiting iron to help their growth." (PMID 38072118, 2023). "The described effects of Lcn2 expression during cancer progression are controversial and highly depend on the tumor type as well as its tissue expression." (PMID 37222464, 2023). "Based on the tumor microenvironment, tumor characteristics and our previous work, we believe that the reduction-responsive nanoplatform is conducive to the delivery of LCN2-siRNA." (PMID 36899380, 2023). "Although Lcn-2 is shown to be highly expressed in certain carcinomas, using Lcn-2 as a therapeutic target has only been tried in the early stages of tumor development." (PMID 37958332, 2023). "When cocultured with LCN2-overexpressed Jurkat cells, the number of HCT116 cells increased, indicating that LCN2 had potential to promote tumor development." (PMID 38072118, 2023). "In return, neutrophils activated by those factors secrete a high level of lipocalin 2 (LCN2), which in turn enhances the stemness of tumor cells." (PMID 37174093, 2023). "In our experiment, both PDT treatment of Se-PC and PC downregulated the gene expressions of S100a9, Slc2a1, and Lcn2 to slow tumor proliferation by regulating cell metabolism and iron binding." (PMID 37994159, 2023). "Our in vitro experiments showed that SERPINA3 and LCN2 suppressed the proliferation of BPCa cells, suggesting that these two genes are tumor suppressors in BPCa; TCGA dataset analysis supported this conclusion." (PMID 37408474, 2023). "Studies have found that LCN2 is involved in the regulation of various tumor functions and can be used as an independent predictor of tumor patient prognosis." (PMID 36899380, 2023). "In a glioma model, Lcn2 expression was induced by tumor-derived exosomes via JAK-STAT3 signaling in bEnd.3 endothelial cells." (PMID 37222464, 2023). "Our study found that lipocalin-2 (LCN2) was significantly upregulated in tumor-infiltrating CD4+ T cells in CRC." (PMID 38072118, 2023). "In TNBC cells, autocrine excretion of LCN2, incited by loss of the tumor suppressor gene HIC1, activated the AKT pathway and caused tumor progression." (PMID 36077676, 2022). "The role of SAA1, accompanied by LCN2 expression, was predicted to lead to tumor suppression in this study." (PMID 35705840, 2022). "In the present study, we provided new insight into LCN2 as a potential biomarker for the prediction of CAC, and demonstrated that LCN2 is a key regulator of cell survival and tumor development mediated by STAT3/NF-kB activation." (PMID 35470375, 2022). "Specifically, our findings demonstrated that the expression of LCN2 and MMP9 was associated with the development of main tumor types." (PMID 36211450, 2022).